PDCD5 (programmed cell death 5)
Synonyms: TFAR19; MGC9294
Tractability: PROTAC: ubiquitination databases record sites on it; its protein half-life has been measured.
Gene: Protein-coding gene on chromosome 19 (32,581,188 to 32,587,453, forward strand). Ensembl gene ENSG00000105185.
Subcellular location: Nucleus; Cytoplasm, cytosol
Subcellular location (Human Protein Atlas): Cytosol; Nucleoplasm
Gene Ontology:
Molecular function: acetyltransferase activator activity; beta-tubulin binding; heparin binding; protein binding; protein sequestering activity; DNA binding
Biological process: cellular response to transforming growth factor beta stimulus; negative regulation of protein folding; positive regulation of apoptotic process; regulation of apoptotic process; T cell activation
Cellular component: cytoplasm; extracellular exosome; nucleus; cytosol
Genetic constraint (gnomAD): Loss-of-function variants: 16 observed, 12.4 expected, observed/expected ratio (o/e) 1.29, 90% interval 0.87 to 1.84. The upper end of that interval is the gene's LOEUF score, 1.84, which puts it in group 6 of 6, group 1 being the genes least tolerant of losing a copy. Missense variants: 100 observed, 72.75 expected, observed/expected ratio (o/e) 1.37, 90% interval 1.17 to 1.62. Synonymous variants: 27 observed, 22.88 expected, observed/expected ratio (o/e) 1.18, 90% interval 0.87 to 1.62.
Homologues: Orthologues: macaque PDCD5 (100% identical), guinea pig PDCD5 (96% identical), pig PDCD5 (96% identical), rabbit PDCD5 (94% identical), rat Pdcd5l1 (86% identical), mouse Pdcd5 (84% identical), zebrafish pdcd5 (82% identical), tropical clawed frog pdcd5 (81% identical), dog PDCD5 (66% identical), Drosophila melanogaster PDCD-5 (46% identical), Caenorhabditis elegans D2005.3 (42% identical).
Diseases named in the same sentence as PDCD5 in open-access papers:
PDCD5 is named in the same sentence as 52 diseases in open-access papers, as found by Europe PMC text mining. Sharing a sentence is not in itself a finding about the gene and the disease. The quoted sentences say what the papers report.
gastric cancer (6 papers, 2015 to 2025). A primary or metastatic malignant neoplasm involving the stomach. "PITX1 binds to the target gene PDCD5, which is an apoptosis related gene, so the down-regulation of PITX1 is associated with poor prognosis in gastric cancer." (PMID 32830857, 2020). "Moreover, the reduced expression of PDCD5 was related to short survival periods of patients with gastric cancer and ovarian serous carcinoma." (PMID 27398268, 2016). "It has been reported that PDCD5 mRNA and protein were both downregulated in some human tumor tissues such as breast cancer, ovarian carcinoma, gastric cancer, hepatocellular carcinoma, acute and chronic myeloid leukemia, glioma and laryngeal squamous cell carcinoma." (PMID 27398268, 2016). "In gastric cancer, PITX1 induces apoptosis and inhibits cell proliferation by binding to the apoptosis-related gene PDCD5 promoter and blocking the cell cycle in G1/S phase." (PMID 40342824, 2025). "PDCD5 can induce HDAC3 cleavage and ubiquitin-dependent proteasome degradation, which is relevant to unfavorable prognosis of gastric cancer patients." (PMID 36266728, 2022). "In gastric cancer, decreased expression of PITX1 can predict shorter overall survival; it is also known that PITX1 binds to the apoptosis-related target gene PDCD5 to suppress GC cell proliferation." (PMID 34868397, 2021).
hepatocellular carcinoma (6 papers, 2015 to 2023). A malignant tumor that arises from hepatocytes. "The overexpression of PDCD5 sensitizes hepatocellular carcinoma cells to cisplatins and reduces cell invasion (Fan, Yao, Yao, & Li, 2015)]." (PMID 32248621, 2020). "The present study aims to investigate the biological behavior of PDCD5 overexpression in hepatocellular carcinoma (HCC) cells." (PMID 25436001, 2015). "In addition, in hepatocellular carcinoma, the PDCD5 overexpression stimulates the promoter activity of KLF9, and the upregulation of KLF9 inhibits cell migration and proliferation." (PMID 36033519, 2022).
lung carcinoma (6 papers, 2015 to 2020). "PDCD5 shows a higher mutation rate in lung cancer patients with shorter survival." (PMID 32248621, 2020). "Collectively, these data demonstrate that PPEF-1 plays a pivotal role in tumorigenesis of lung cancer cells by reducing PDCD5-mediated genotoxic stress responses." (PMID 28051100, 2017). "In an effort to study the role of PDCD5 in the DNA damage response, we first investigated the transcriptional regulation of PDCD5 in Hct116 colon carcinoma, A549 lung carcinoma and U2OS osteosarcoma cells." (PMID 26062895, 2015).
glioma (4 papers, 2015 to 2020). A benign or malignant brain and spinal cord tumor that arises from glial cells (astrocytes, oligodendrocytes, ependymal cells). "In glioma, the expression of PDCD5 was significantly reduced in highly malignant cases, making PDCD5 a tumor suppressor (Wang, Li, Li, & Gong, 2018)." (PMID 32248621, 2020). "Previous reports showed that the decreased expression of PDCD5 significantly correlated with the high-grade tumor in renal clear cell carcinomas and gliomas." (PMID 27398268, 2016). "The decreased expression of PDCD5 has been reported in various human tumors, including prostate, lung and ovarian cancer, gliomas and leukemia." (PMID 25436001, 2015). "PDCD5 also enhances apoptosis by cooperating with cisplatin [cis-diamminedichloroplatinum(II)] in certain tumor cells, including those of colorectal cancer, gastric cancer and glioma." (PMID 25436001, 2015).
ovarian carcinoma (4 papers, 2015 to 2024). A malignant neoplasm originating from the surface ovarian epithelium. "Though there are fewer defined roles for ovarian PDCD5, there are links with ovarian pathology including ovarian cancer and granulosa cell apoptosis." (PMID 38666409, 2024). "Furthermore, downregulated PDCD5 is indicative of dismal pathological features of patients with ovarian cancer." (PMID 36266728, 2022).
Arthritis (3 papers, 2015 to 2017). Inflammation of a joint. "Since the immune function of CFA, the serum levels of IFN-γ, IL-6, IL-17A and TNF-α in PDCD5 tg mice and their arthritis control were significantly increased, however the production of pro-inflammatory cytokines in PDCD5 tg mice were relatively inhibited." (PMID 29228993, 2017). "Simultaneously, the expression of IL-4 in PDCD5 tg mice was higher than their normal control and arthritis control." (PMID 29228993, 2017). "Recombinant PDCD5 protein intraperitoneal injection can protect the joint against inflammatory destruction evoked by collagen-induced arthritis in rats." (PMID 29228993, 2017). "Next, we found that the proportion of Th1 and Th17 in PDCD5 tg mice and their arthritis control were increased compared than TC and NC, respectively." (PMID 29228993, 2017). "In the present study, PDCD5 tg mice demonstrated protective effects on clinical symptoms during AIA compared with arthritis control mice." (PMID 29228993, 2017). "In the current study, PDCD5 tg mice inhibited the progression of adjuvant-induced arthritis, specifically decreasing clinical signs and histological damage, compared with arthritis control mice." (PMID 29228993, 2017). "Later the authors found the anti-inflammatory effects of recombinant human PDCD5 (rhPDCD5) in a rat collagen-induced arthritis model and provided the comprehensive assessment of immunosuppressive pathways of rhPDCD." (PMID 27846830, 2016). "This partially explains the protective effects of PDCD5 on adjuvant-induced arthritis in mice." (PMID 29228993, 2017). "In addition, compared with arthritis control, PDCD5 tg mice reduced serum levels of the pro-inflammatory cytokines IFN-γ, IL-6, IL-17A and TNF-α and upregulated the expression of the anti-inflammatory cytokine IL-4." (PMID 29228993, 2017). "PDCD5 tg mice did not demonstrate a reduced incidence of AIA; however, significant reductions in arthritis score, joint circumference and paw oedema were observed compared with arthritis control mice." (PMID 29228993, 2017).
breast carcinoma (3 papers, 2016 to 2024). "Furthermore, when extracting the co-expression gene list from TCGA and METABRIC datasets, we observed that LSM2 was closely co-expressed with various breast cancer biomarkers such as PDCD5 and NUDT5." (PMID 34638387, 2021).
pulmonary fibrosis (3 papers, 2021 to 2025). Chronic progressive interstitial lung disorder characterized by the replacement of the lung tissue by connective tissue, leading to progressive dyspnea, respiratory failure, or right heart failure. "The molecular mechanisms through which club cells mediate pulmonary fibrosis in IPF are linked primarily to programmed cell death 5 (PDCD5)." (PMID 41409095, 2025). "Here the authors investigate the functional significance of PDCD5 in club cells as a mediator of lung fibrosis and potential therapeutic target for IPF." (PMID 34011956, 2021). "Using mice with club cell-specific Pdcd5 conditional knockout (Ccsp-Pdcd5d/d) and AT2 cell-specific Pdcd5 conditional knockout (Spc-Pdcd5d/d), we show that PDCD5 plays a selective role in club cells during pulmonary fibrosis initiation." (PMID 34011956, 2021). "We found that BLM significantly induced lung fibrosis and PDCD5 expression starting 3 days after injection." (PMID 34011956, 2021). "Collectively, these data demonstrate that club cell-specific PDCD5 mediates fibroblast activation by promoting secretion of matricellular proteins, which eventually leads to pulmonary fibrosis." (PMID 34011956, 2021). "The induction of lung fibrosis following BLM injection was significantly suppressed by deletion of Pdcd5 gene from 2 days after first 4-OHT injection." (PMID 34011956, 2021). "Our findings highlight the functional significance of PDCD5 in pulmonary fibrosis and suggest a conceptual framework for understanding the interconnectivity between club cells and pulmonary fibrosis." (PMID 34011956, 2021). "To further validate the functional role played by PDCD5 in the initiation of pulmonary fibrosis, we performed the genetic deletion of Pdcd5 after the induction of lung fibrosis." (PMID 34011956, 2021). "Here, we demonstrate the club cell-specific role of PDCD5 as a mediator of lung fibrosis and potential therapeutic target for IPF." (PMID 34011956, 2021). "Our results suggest that PDCD5 acts as a pulmonary fibrosis mediator in a club cell-specific manner." (PMID 34011956, 2021). "The deletion of Pdcd5 in club cells significantly alleviates pulmonary fibrosis in a murine model." (PMID 41409095, 2025). "Lung fibrosis is significantly diminished by club cell-specific deletion of Pdcd5 gene." (PMID 34011956, 2021). "We next examined the molecular mechanism by which PDCD5 mediates lung fibrosis in club cells." (PMID 34011956, 2021). "Consequently, we identified the physiological roles of PDCD5 in club cells and our results suggest that club cells have a significant functional role in pulmonary fibrosis." (PMID 34011956, 2021). "Collectively, our results demonstrate that PDCD5 is significantly elevated in the lungs of patients with IPF and in mice with pulmonary fibrosis." (PMID 34011956, 2021). "We show that programmed cell death 5 (PDCD5) expression is increased in the lungs of patients with IPF and in mouse models of lung fibrosis." (PMID 34011956, 2021). "In this study, we found elevated expression of PDCD5 in the lungs of patients with IPF and mouse models of lung fibrosis." (PMID 34011956, 2021). "We provided evidence that PDCD5 selectively mediates pulmonary fibrosis in a club cell-specific manner, but not in AT2 cells or fibroblasts." (PMID 34011956, 2021). "To further verify induction of PDCD5 expression in TGF-β-driven lung fibrosis, we next evaluated changes in PDCD5 expression in a transgenic mouse model with inducible overexpression of TGF-β1 (Ccsp-TGFβ1-TG mice), which induces lung fibrosis after administration of doxycycline (Dox)." (PMID 34011956, 2021). "Taken together, our results suggest that PDCD5 mediates lung fibrosis initiation, without affecting club cell death and proliferation." (PMID 34011956, 2021). "However, the role of PDCD5 in pulmonary fibrosis has not been explored." (PMID 34011956, 2021).
pulmonary fibrosis (continued). "Moreover, strengthening a potential role of apoptotic SCGBB1A1+ secretory cells in IPF, a recent report has demonstrated that ablation of programmed cell death 5 (PDCD5) expression in these secretory cells, but not in AT2 cells protects from experimental lung fibrosis." (PMID 35326501, 2022).
rheumatoid arthritis (3 papers, 2015 to 2018). A chronic, systemic autoimmune disorder characterized by inflammation in the synovial membranes and articular surfaces. "PDCD5 was found involved in some autoimmune diseases and inflammatory processes, such as rheumatoid arthritis and psoriasis." (PMID 27846830, 2016). "Clinically, PDCD5 is involved in some autoimmune diseases and inflammatory processes such as lupus nephritis, rheumatoid arthritis, osteoarthritis, hepatitis and sepsis." (PMID 27846830, 2016). "For example, similar to our results, PDCD5 levels in serum and synovial fluid of rheumatoid arthritis (RA) patients have been found to be significantly higher compared with HC, and a negative correlation of its levels with disease activity indices has been described." (PMID 29527211, 2018).
allergic asthma (2 papers, 2016 to 2019). A asthma with a basis in a pathological type I hypersensitivity reaction. "In the present study, we established a mouse model of allergic asthma to investigate the effect of tiotropium on the change in asthmatic pathology and the expression of PDCD5." (PMID 31662808, 2019). "Here we established a mouse model of allergic asthma and further explored the significance of PDCD5 in bronchial asthma." (PMID 27846830, 2016). "This study aimed to further explore the significance of PDCD5 in mice with induced allergic asthma." (PMID 27846830, 2016). "Considering the consistent correlation between PDCD5 expression and severity of asthma from clinical research to animal models, although we cannot regard PDCD5 as a potential biomarker for monitoring and controlling asthmatic severity, PDCD5 may play a role in allergic asthma." (PMID 27846830, 2016). "We previously demonstrated increased expression of programmed cell death 5 (PDCD5) in asthmatic patients and ovalbumin-induced allergic asthma." (PMID 31662808, 2019). "Our previous study of PDCD5 in asthma patients did not specify whether asthmatic patients were allergic or not, whereas the mouse model in this study is an allergic asthma model." (PMID 27846830, 2016).
asthma (2 papers, 2016 to 2019). "The consistent correlation between PDCD5 expression and severity of asthma indicated not only the potential role of PDCD5 in monitoring asthmatic severity but also a correlation between tiotropium and apoptosis." (PMID 31662808, 2019). "We previously found serum PDCD5 level higher in patients with asthma than controls and negatively correlated with several indexes of lung function." (PMID 27846830, 2016). "We found a correlation between PDCD5 expression and severity of asthma in OVA-induced asthmatic mice." (PMID 27846830, 2016). "Finally, the expression of PDCD5 was correlated with asthma severity and active caspase-3 levels." (PMID 31662808, 2019). "Moreover, activated caspase-3 level was increased and correlated with PDCD5 level in asthma." (PMID 27846830, 2016). "In the present study, our results imply a correlation between asthma and apoptosis and confirm that PDCD5 participates in airway inflammation and airway remodeling of asthma; downregulated expression of PDCD5 could reflect the relief of airway inflammation and remodeling." (PMID 27846830, 2016). "However, few studies have investigated the role of PDCD5 in asthma." (PMID 27846830, 2016). "Our previous studies reported increased serum PDCD5 level in asthmatic patients and upregulated PDCD5 in BALF and lung tissue of untreated asthmatic mice versus controls, which was correlated with asthma severity." (PMID 31662808, 2019). "However, few studies have focused on whether and how PDCD5 is involved in asthma." (PMID 27846830, 2016).